RNU6-457P (RNA, U6 small nuclear 457, pseudogene)
Gene: Small nuclear RNA gene on chromosome 16 (6,873,899 to 6,874,005, forward strand). Ensembl gene ENSG00000200869.
Homologues: Orthologues: chimpanzee U6 (97% identical), macaque U6 (85% identical). Paralogues in human: RNU6-211P (90% identical), RNU6-154P (89% identical), RNU6-20P (89% identical), RNU6-310P (89% identical), RNU6-35P (89% identical), RNU6-1152P (88% identical), RNU6-1316P (88% identical), RNU6-16P (88% identical), RNU6-25P (88% identical), RNU6-820P (88% identical), RNU6-1 (87% identical), RNU6-144P (87% identical), and 1285 more.